MMP9 (matrix metallopeptidase 9)
Diseases named in the same sentence as MMP9 in open-access papers (continued):
Sharing a sentence is not in itself a finding about the gene and the disease.
tumor (continued). "Proteolytic enzymes MMP-2 and MMP-9 are overexpressed in cancer, resulting in increased tumor migration and invasion." (PMID 35875198, 2022). "The antitumor activity of SB-3CT was tested in a mouse model of T-cell lymphoma, characterized by high MMP9 expression, where a significant reduction in tumor growth was observed." (PMID 35406619, 2022). "MMP-9 is a key protease to remodel and degrade extracellular matrix, and it has been reported that MMP-9 plays a vital role in tumor development and progression and participates in EMT process." (PMID 35470736, 2022). "Matrix metalloproteinases (MMPs), including MMP2 and MMP9, have been previously reported to promote cell migration and tumour metastasis." (PMID 35811356, 2022). "The pro-angiogenic role of MMP-9-secreting neutrophils in tumor vascularization was also validated in other types of cancer." (PMID 35158807, 2022). "In HNSCC MMP-9 plays an important role during tumor invasion, as well as the participation of ERK-1/2 and PI3K signaling pathways." (PMID 35890188, 2022). "Here, we calculated the TMB of each tumor sample and analyzed the correlation between MMP-9 and TMB in 33 tumors." (PMID 35178444, 2022). "MMP9 is an important member of the matrix metalloproteinase family, and mouse studies have shown that this enzyme plays a role in tumour-related tissue remodelling." (PMID 35513781, 2022). "In penile cancer, enforced expression of CXCL13 stimulates tumor metastasis by inducing the expression of metastasis-related MMP2/MMP9 through STAT3 and ERK1/2 signaling pathways." (PMID 36612163, 2022). "Tumor metastases begin with basement membrane degradation by matrix metalloproteinases (MMPs), such as MMP2 and MMP9, followed by tumor extravasation and dissemination, and finally colonization in new lesions." (PMID 36612163, 2022). "Because the MMP9 plasma level was correlated with MMP9 tumor expression, we analyzed the correlation between plasma MMP9 level and tumor volume." (PMID 34980260, 2022). "MMP-9 expression was increased in tumor tissue of invasive PTC with a statistically significant increase of expression in the adjacent non-tumorous tissue of invasive PTC in our study." (PMID 36551933, 2022). "We additionally determined the activity of matrix metalloproteases (MMP2 and MMP9), since MMPs are critical for tumor invasion in many types of cancer, including GBM." (PMID 35682709, 2022). "The role of GEMIN in tumor development through the GEMIN3—NF-κB—MMP9 axis is complicated by the fact that the role of GEMIN3 in carcinogenesis is different for different types of cancer." (PMID 36405016, 2022). "The results of the mouse model showed that O-NP was preferentially accumulated and endocytosed in MMP9-expressing tumors, which began to exert anti-tumor effects and effectively reduce the toxicity of normal tissues." (PMID 36145668, 2022). "In our study, we used for the first time a large cytometry panel to refine the expression profile of MMP9 in five fresh tumor samples at diagnosis and observed that MMP9 was mainly released by tumor-infiltrating neutrophils." (PMID 34980260, 2022). "Obviously, the addition of JM2 in the cell culture medium significantly suppressed the gene expressions of MMP2 and MMP9 in both types of tumor cells." (PMID 35332127, 2022). "Quantitative RT-PCR and gelatin zymography demonstrated low to medium expression levels of MMP-2 and/or MMP-9 in some tumor cells and their absence in others." (PMID 36539774, 2022). "It is well known that MMP-9 has a close link with metastasis, and inhibiting the expression of MMP-9 can prevent tumor metastasis." (PMID 35954126, 2022). "The loss of miR-155 in MDSCs improved T-cell function and decreased Arg-1, iNOS, Vegf, and Mmp-9 expression, all of which are involved in immune suppression, tumor vascularization, and metastasis." (PMID 36248881, 2022). "MMP9 is widely expressed in various malignant tumors, and it promotes tumor invasion and migration by degrading the extracellular matrix." (PMID 35048517, 2022).
tumor (continued). "Crucially, MMP2 and MMP9 expression is often upregulated in tumours and their degradation of components like proteoglycans can release bound bioactive components termed matrikines or matricryptins." (PMID 36045675, 2022). "At the same time, TAN-N2 presents an anti-inflammatory profile, exhibiting higher levels of CD184 (CXCR4), arginase-1, CCL2, CCL5, VEGF, IL-8, and MMP-9, supporting tumor growth, invasion, and metastasis." (PMID 35741003, 2022). "Members of the MMP family, MMP2 and MMP9, play a key role in tumour invasion, metastasis and angiogenesis." (PMID 35000605, 2022). "The expression of certain MMPs results in poorer prognosis; for example, increased MMP-9 expression positively correlates with metastatic profile, degree of tumor necrosis, and the formation of metastases." (PMID 35457074, 2022). "The latest research claims that lncRNA-PVT1 as a tumor gene participates in the generation and development of tumors by regulating matrix metalloproteinase MMP9." (PMID 36164442, 2022). "Matrix metalloproteinase (MMP) is a type of enzyme that promotes tumor cells metastasis, and MMP-2 and MMP-9 are commonly used as tumor metastasis indicators." (PMID 35957875, 2022). "The function of MMP9 is closely related to tumor invasion and metastasis through its functional degradation of type IV and V collagen and gelatin." (PMID 35431936, 2022). "MMP-2 (Gelatinase A) and MMP-9 (Gelatinase B) are known to significantly contribute to tumor invasion and progression through their proteolytic actions." (PMID 36230480, 2022). "By binding to transmembrane proteins (αβ integrins, CD44, EGF receptor/EGFR), MMP2 and MMP9 directly trigger intracellular signalling pathways that control tumour cell events." (PMID 35158891, 2022). "This acidification drives the increased expression and activation of matrix metalloproteases (MMP2 and MMP9), which proteolytically cleaves extracellular matrix proteins driving matrix degradation and tumor cell invasion." (PMID 35686673, 2022). "It has been reported that p‐AKT activation is crucial in HCC progression, and MMP2 and MMP9 are involved in tumour invasion and metastasis." (PMID 35811356, 2022). "MMP-9 was found to be overexpressed in a variety of tumors, and its expression is positively correlated with tumor cell invasion and migration." (PMID 35956952, 2022). "This feature has been well demonstrated in several works, comprising selective inhibition and MMP-9-deficient mice, all of which pointed to MMP-9 as an important target of neoplastic diseases." (PMID 36551666, 2022). "Studies have shown that MMP9 is overexpressed in various cancers and is related to tumor metastasis and invasion." (PMID 35562740, 2022). "Meanwhile, the proliferation marker Ki67 and the invasion and migration marker MMP9 were significantly decreased in the tumour tissues of nude mice." (PMID 35013157, 2022). "Taken together, two tumor antigens (MMP9 and IGF2BP2) were identified as promising candidates for developing mRNA vaccines against BLCA." (PMID 36569935, 2022). "The correlation analysis was also carried out between the methylation levels and expression of LCN2, SLC22A17, and MMP9 in each tumor type." (PMID 36211450, 2022). "The synergistic activation of these MMPs modulators only induces an additive reduction of the MMP-2 and MMP-9 activities, suggesting MMPs should be a critical control point for the ability of lung metastasis of the xenografted tumor." (PMID 35711540, 2022). "MMP-9 has been found to be closely related to immunity and tumor progression; however, most studies have focused on single cancers." (PMID 35178444, 2022). "Subsequently, we stimulated peripheral blood neutrophils with these supernatants and determined neutrophil survival as well as the release of MMP9—both indicators of a pro-tumor neutrophil phenotype." (PMID 35682709, 2022).
tumor (continued). "The current study reports significantly high levels of MMP-9 in tumor tissues as compared to adjacent normal tissues in local as well as TCGA cohort." (PMID 36309544, 2022). "Among the members of MMP family proteins, MMP-2 and MMP-9 are considered to play important roles in the metastasis of tumor cells." (PMID 36483979, 2022). "The research results show that lncRNA-PVT1 can interfere with tumor growth rate by regulating the expression of MMP9." (PMID 36164442, 2022). "MMP2 and MMP9 can hydrolyse basement membrane components and regulate various aspects of tumour growth and metastasis." (PMID 36408277, 2022). "Tumor cells can primarily express MMP-2 and MMP-9 to debase type IV collagens and disrupt these tissue barriers, which stimulates tumor cell invasion and metastasis." (PMID 35747793, 2022). "Among MMPs, MMP‐2 and MMP‐9 are mostly associated with ECM degradation and promote tumour cell invasion and metastasis." (PMID 35775112, 2022). "This suggest that in the cross-talk between microglia and tumor cells, there is a MMP9-promoting pathway complementary to TLR2." (PMID 35992852, 2022). "Under the action of MMP9 in the tumor microenvironment, the surface charge of O-NP was successfully reversed from negative to positive." (PMID 36145668, 2022). "Neutrophil elastase and MMP9 cleave laminin, create a specific environment that can activate dormant tumor cells, while, circulating tumor cells reach the distant tissue through the disrupted vasculature." (PMID 36114508, 2022). "Tumor cell-produced MMP-9 was shown to promote metastasis in an orthotopic mouse model of basal-like TNBC." (PMID 36741729, 2022). "For example, MMP9, a matrix metalloproteinase, is involved in the degradation of the extracellular matrix and connected to tumor cell invasion and metastasis." (PMID 35186752, 2022). "Based on this, we conducted a number of experiments to show that HB-derived exosomal lncRNA NEAT1 induced BMSCs to differentiate into tumor-supporting myofibroblasts by regulating the miR-132/MMP9 axis." (PMID 35300348, 2022). "Matrix metalloproteinase-9 (MMP-9) can degrade the extracellular matrix and participate in tumor progression." (PMID 35178444, 2022). "Accumulating evidence suggested that MMP9 played a key positive role in OSCC (oral squamous cell carcinoma) tumor cells migration and invasion across the basement membrane." (PMID 36091137, 2022). "In liver cancer cells, mRNA expression of MMP-2 and MMP-9 is up-regulated as a result of the inhibition of miR-21, which stimulates the invasion and migration of tumor cells." (PMID 36776395, 2022). "In another way, Fn-attracted MDSCs reduce infiltration of T cells into the tumor and increase expression and promote secretion matrix metalloproteinase 9 (MMP-9) and MMP-13 to promote angiogenesis." (PMID 35800370, 2022). "In the tumor microenvironment, TANs were also demonstrated to generate matrix metalloproteinase-9 (MMP-9) to orchestrate sequestered VEGF from the ECM in dysplastic pancreatic islet lesions of Rip1Tag2 transgenic mouse model." (PMID 36439137, 2022). "PC is generally hypoxic due to its avascular morphology, and PC cells express high levels of HIF-1α and MMP-9 for promoting tumor growth, invasion and metastasis in a hypoxic environment." (PMID 35681664, 2022). "On these bases, the role of LCN2, SLC22A17, and MMP9 was evaluated in different tumor types performing in silico analysis using the expression and methylation data available on TCGA and GTEx datasets." (PMID 36211450, 2022). "MUC4 was expressed homogeneously within the entire tumor parenchyma, mostly in the tumor cell cytoplasm, with less restricted localization than MMP9." (PMID 36400876, 2022). "In other tumor types, MMP9 was previously reported to be expressed by immune cells, such as pathogenic M2 macrophages, tumor-infiltrating neutrophils or myeloid-derived suppressor cells." (PMID 34980260, 2022).
tumor (continued). "As a key proteolytic enzyme, MMP9 produced by cancer cells and extracellular matrixes (ECMs) surrounding the tumor can activate angiogenic factors such as VEGF, leading to increased angiogenesis and metastatic activities." (PMID 35386201, 2022). "The same tumor cells that secrete MMPs also synthesize TIMPs, the imbalance of MMP-9: TIMP1 makes tumor cells more invasive." (PMID 36158681, 2022). "Many studies have shown that MMP-9 plays a role in promoting cancer development and progression through influencing the tumor microenvironment." (PMID 36242015, 2022). "AITC significantly downregulated the protein expression levels of MCL-1, XIAP, MMP-9, and VEGF; however, it increased apoptosis-associated proteins, such as cleaved caspase-3, -8, and -9, in the tumor tissues compared with the control group." (PMID 36142326, 2022). "More specifically, MMP-9 expression was positively correlated with IL-10 (a TAM marker), which is often associated with tumor immune evasion." (PMID 35178444, 2022). "Data showed that MMP2 and MMP9 expression was positively correlated to tumour invasion depth, venous invasion and increased tumour size (over 4cm)." (PMID 36045675, 2022). "There are potent tumor promoters that can induce MMP-9 expression through various intracellular signaling pathways." (PMID 35840633, 2022). "Herein, we detected the expression of MMP-9, CD147, MMP-2, as well as VEGF protein linked to tumor cell migration along with infiltration in MDA-MB-231 cells via Western blot experiment." (PMID 35295962, 2022). "Volcano plot analysis of OS revealed that MMP9 was an unfavorable prognostic factor in five tumor types (ACC, KIRC, LGG, LIHC, and UVM), while it was favorable only in BRCA and DLBC." (PMID 36211450, 2022). "In tumor cells, MMP-9 contributes to the remodeling of extracellular matrix proteins, providing a microenvironment for tumorigenesis." (PMID 36204126, 2022). "Proteomics analysis of tumor-associated sEVs revealed that sEVs release proteins, including SERPINA1, SERPINF2, and matrix metalloproteinase 9 (MMP9), which are involved in extra cellular matrix remodeling, vascular leakage, and aggressiveness." (PMID 36499561, 2022). "There is a study on the correlation between MSN and MMP9 showed that, in individual tumours, the expression of MSN and MMP9 remains consistent, which jointly promotes tumour metastasis." (PMID 35557941, 2022). "The simplest explanation would be that the even though drastically reduced, MMP9 levels in CD44-/- GAMs are still sufficient to promote tumor invasion." (PMID 35992852, 2022). "MMP-9 is an essential cytokine for the invasion and metastasis of tumor cells and also the largest-molecular-weight enzyme in MMPs, which can degrade ECM and the major structural protein (collagen IV) of the basement membrane." (PMID 35361045, 2022). "Our western blotting results showed that Gleditsiae Spina significantly inhibits the expression of MMP9 to reduce tumor cell activity." (PMID 35299895, 2022). "MMP-9 can cleave type IV collagen, the main component of the basement membrane, so it plays an important role in tumor invasion." (PMID 35361045, 2022). "MMP9 expression was also seen in different amounts at the tumour stroma near the tumour border and scored as abundant (n=15, 24%), sporadic (n=34, 55%), or negative (n=13, 21%)." (PMID 35756604, 2022). "MMP2 can degrade the basement membrane, and MMP9 can induce tumor cells to infiltrate and migrate to surrounding tissues along the damaged basement membrane." (PMID 35468097, 2022). "MTX is linked to DEX by a peptide that can be cleaved by matrix-metalloproteinase-2 (MMP-2) and matrix-metalloproteinase-9 (MMP-9), two important enzymes present in tumor tissue." (PMID 36145522, 2022). "In the follow-up period, three patients developed NMSC and experienced an increase in MMP-9 levels at the time of neoplasm removal compared to basal." (PMID 36293148, 2022).
tumor (continued). "Pro-tumoral N2 neutrophils play a key role in the formation of metastases by secreting MMP9 and neutrophil elastase (NE) to favor the remodeling of the extracellular matrix necessary for tumor progression." (PMID 35163180, 2022). "Mast cells can release angiogenic-mediated VEGF by mediating MMP-9 in the tumor microenvironment after low-dose radiation therapy." (PMID 35251963, 2022). "In contrast, mean ADAM8 and MMP9 expression levels were upregulated in the investigated tumor samples." (PMID 35371977, 2022). "This recruitment of neutrophils upregulates the expression of MMP9 and MMP-9+ neutrophils play a functional and concomitant role in tumor cell angiogenesis and intravasation." (PMID 35784290, 2022). "Matrix metalloproteinases MMP2 and MMP9 can induce the degradation of extracellular matrix components, promoting tumor cell infiltration and spread in the bloodstream." (PMID 35893303, 2022). "Our results demonstrated that LCN2 and MMP9 were mainly upregulated in most tumor types, whereas SLC22A17 was largely downregulated, representing a specific hallmark signature for all gastrointestinal tumors." (PMID 36211450, 2022). "In contrast to Lrp5-overexpressing osteocytes, Lrp5-overexpressing astrocyte-derived CM promoted the viability and migration of EO771 tumor cells, and the level of MMP9, Runx2, and Snail in EO771 cells were upregulated." (PMID 33802279, 2021). "The decreased FoxO3a expression in tumour cells was reported to be associated with decreased MMP1, MMP9 and MMP13 levels and inhibited invasion and migration." (PMID 33811439, 2021). "Loss of SMAD4 promotes expression of CCL15 by CRC and recruitment of CCR1+ TANs (CCL15-CCR1 axis) with both arginase-1 (ARG-1) and matrix metalloprotease 9 (MMP-9) activity, forming a premetastatic niche for the disseminated tumor cells —e.g., in the lungs." (PMID 33917620, 2021). "Expression of matrix metalloproteinases (MMPs) 2 and MMP9, as well as lysyl oxidase (LOX) are deemed important contributors to tumor invasion and metastasis, and are linked to the Wnt/β-catenin pathway." (PMID 34638991, 2021). "The αVβ3-SDC-1 interaction is likely necessary for FAK activation and the subsequent upregulation of MMP-2 and MMP-9, important steps in tumor metastasis." (PMID 35118073, 2021). "Previous studies showed that the expression levels of MMP2, MMP7 and MMP9 is positively correlated with the plasticity of tumor cells, such as invasion depth, metastasis distance, and vascular permeability." (PMID 34696818, 2021). "Recent data indicate that LH3 is a novel MMP-9 docking receptor on the cell surface of fibroblasts in the tumor stroma." (PMID 33807594, 2021). "Our findings suggest a pivotal role of let-7f in the cytokine/chemokine-mediated tumor tropism of hMSCs involving its positive regulation of MMP-9 and CXCR4." (PMID 34016957, 2021). "S100A7, which is frequently overexpressed in ERα− breast cancer, stimulates tumor growth by recruiting MMP9-positive pro-tumor macrophages." (PMID 34572138, 2021). "The 65 kDa isoform of MMP-9 is a suitable biomarker to monitor tumor progression from tissue neoplasms to metastatic stage, as its activity begins to appear when disease severity increases and becomes very high in metastasis." (PMID 35723387, 2021). "It has also been shown that SCA inhibits the secretion of interleukin-8, downregulates the protein expression of VEGF and MMP-9, inhibits the formation of new blood vessels, inhibits tumor cell adhesion, thereby inhibiting tumor invasion and metastasis." (PMID 34976813, 2021).